MMP9 (matrix metallopeptidase 9)
Diseases named in the same sentence as MMP9 in open-access papers (continued):
Sharing a sentence is not in itself a finding about the gene and the disease.
pancreatic cancer (continued). "Of the 103 pancreatic cancers, the expression levels of MMP-9 were high in 61 samples and low in 42 samples, and the expression of TN-C was high in 56 samples and low in 47 samples." (PMID 26652622, 2015). "Multivariate analysis showed that the co-expression of MMP-9 and TN-C was an independent predictor for the survival of pancreatic cancer patients." (PMID 26652622, 2015). "In this study, we only focus on the relation of MMP-9, total TN-C and fTN-C in pancreatic cancer invasion, we found that the expression of MMP-9 and TN-C was increased in all pancreatic cancer tissues compared with normal pancreatic tissue." (PMID 26652622, 2015). "To determine the effects of MMP-9 and TN-C on the survival rates of pancreatic cancer patients, we used Log-rank test analyses." (PMID 26652622, 2015). "Our data demonstrate that embelin can inhibit/reverse pancreatic tumor metastasis by inducing the expression of E-cadherin and inhibiting its associated transcription factors (Snail, Slug, and ZEB1) and MMPs (MMP-2 and MMP-9)." (PMID 24694877, 2014). "Durlik and Gardian found that MMP-9 is activated only in higher tumor grades of human pancreatic cancer." (PMID 24204396, 2013). "Matrix metalloproteinase-9 (MMP-9, also known as gelatinase B) in particular is highly expressed in both clinical and experimental models of pancreatic cancer." (PMID 23737761, 2013). "Our results show that PPARβ/δ activation by GW501516 suppresses expression of MMP-9 in human pancreatic cancer cells via BCL-6, with further inhibition on the ability of two cell lines, Miapaca-2 and BxPc-3, to invade a basement membrane." (PMID 23737761, 2013). "Previously, α-mangostin has been shown to suppress the phosphorylation of ERK, leading to the inhibition of MMP-2 and MMP-9 in pancreatic cancer cells." (PMID 23833675, 2013). "In human pancreatic cancer tissue there was significantly higher expression of MMP-9 and PPARβ/δ, and lower levels of BCL-6 mRNA." (PMID 23737761, 2013). "Previous evidence, however, establishes a clear link between PPARβ/δ, BCL-6, and MMP-9, and we sought to elucidate the role(s) of PPARβ/δ activation on potential target genes involved in pancreatic cancer invasion and metastasis." (PMID 23737761, 2013). "IL-1β induces MMP-9 expression in other cell lines and enhances the invasiveness of human pancreatic cancer cells." (PMID 23737761, 2013). "Our results demonstrate that the proadhesion molecules E-selectin, ICAM-1, and VCAM-1, the pro-inflammatory IL-1β and MCP-1, and the prometastasis gene MMP-9 are BCL-6-regulated genes in human pancreatic cancer cells." (PMID 23737761, 2013). "Because MMP-9 is a key regulator of human pancreatic cancer cell invasion and metastasis, we further examined the effect of lentiviral shRNA-mediated MMP-9 knockdown on the basal ability of Miapaca-2 cells to invade a basement membrane." (PMID 23737761, 2013). "The mean concentration of MMP-2 and MMP-9 in blood of pancreatic cancer patients is significantly higher than in the control group." (PMID 23768069, 2013). "Knocking down PPARβ/δ in human pancreatic cancer cells reduced MMP-9 protein levels to those comparable to GW501516-treated control cells despite PPARβ/δ activation." (PMID 23737761, 2013). "Since MMP-9 plays a central role in pancreatic cancer invasion, we examined its mRNA and protein levels in both cell lines." (PMID 22532830, 2012). "In particular, MMP-9 plays a central role in pancreatic cancer invasion, and its inhibition decreases liver metastasis of pancreatic cancer." (PMID 22532830, 2012). "MMP1, MMP2, MMP7, and MMP9 have also been shown to be expressed in pancreatic tumor, but the effect of cysteamine on protein and mRNA levels for all these MMPs was not examined except for MMP9." (PMID 22532830, 2012). "Taken together, all lines of evidence suggest COX-2/PGE2 pathway is involved in the upregulation of MMP-9 in pancreatic cancer." (PMID 21760774, 2011).
pancreatic cancer (continued). "Our initial findings reveal a positive correlation of mRNA level of COX-2 expression with MMP-9 in pancreatic cancer specimens, and a probable connection between them in cancer cells." (PMID 21760774, 2011). "COX-2 and MMP-9 have been reported to show an overexpression in pancreatic cancer, and thus an attempt to explore the correlation between them has become a target of this study." (PMID 21760774, 2011). "We have previously shown an upregulated expression of MMP-3 and MMP-9 in pancreas cancer tissue, and interestingly both these proteases have type IV collagen as a substrate." (PMID 19491897, 2009). "The connection to MMP-9 is described in a single publication that links up-regulation of neuregulin and MMP-9 in rat pancreatic carcinoma cell lines." (PMID 16901352, 2006). "In the pancreatic cancer environment, MMP-9 hydrolyzed the PEG, exposing the RGD-targeting ligand." (PMID 40284474, 2025). "α-mangostin (>7.5 μM) was found to inhibit MMP-2 and MMP-9 in pancreatic cancer cells." (PMID 38540096, 2024). "Despite the established importance of MMP9 in mediating invasiveness and metastasis in pancreatic cancer, the role of MEP1A in PDACs remains unclear." (PMID 39158384, 2024). "Moreover, MMP9+ TAMs induced EMT in pancreatic cancer by secreting MMP9 to activate protease-activated receptor 1 (PAR1), which allowed tumour cells to escape macrophage-dependent cell death." (PMID 38303024, 2024). "In addition, 5 μM genistein inhibited MMP-2 and MMP-9 expression in Mia-PaCa2 pancreatic cancer cells, as assessed by Western blotting, in a time-dependent manner." (PMID 39335164, 2024). "However, the correlation between MMP9 expression and clinicopathological factors in pancreatic cancer patients remains inconclusive." (PMID 39158384, 2024). "The addition of neutrophils to pancreatic cancer cells can increase the budding rate by more than 2.5 times, indicating that MMP-9 may promote endothelial cell migration." (PMID 39555072, 2024). "Studies have shown that rosmarinic acid blocks the G2/S cycle in pancreatic carcinoma cells by adjusting the communication of cyclin E, BAX and Bcl-2; inhibits the migration and invasion of pancreatic cancer cells through E-cadherin and Matrix metallopeptidase 9 (MMP-9); and inhibits tumor growth." (PMID 38675663, 2024). "MMP9 is a well-studied biomarker in non-small cell lung, cervical, ovarian, and pancreatic cancer." (PMID 37373974, 2023). "The mRNA-miRNA-lncRNA regulatory network predicted that lncRNA SCAMP1 could bind to miR-132-3p and MMP9 in pancreatic cancer cells." (PMID 35992869, 2022). "After 14 days of treatment with bevacizumab (a VEGF inhibitor) and doxycycline (a drug which could inhibit angiogenesis as effectively as MMP-9 inhibitors), the tumor volume in pancreatic cancer mice was significantly reduced." (PMID 36324574, 2022). "Some observations point to Cavin-1 promoting tumor migration in pancreatic cancer cells by cooperating with caveolin-1 but inhibiting invasiveness and metastasis by matrix metalloproteinase 9 (MMP-9) production, neutralizing CAV1 tumor-promoting properties in PC3 pancreatic cancer cells." (PMID 35722492, 2022). "Moreover, the upregulation of miR-221/222 regulates and induces the MMP-9 protein expression in pancreatic cancers." (PMID 36232606, 2022). "The addition of neutrophils to pancreatic cancer cells can increase the budding rate by more than 2.5 times because MMP-9 may promote endothelial cell migration." (PMID 36324574, 2022). "Wang also found that TQ combined with GEM could significantly inhibit the expression of XIAP and MMP-9 in pancreatic cancer tissues, thereby affecting the growth and metastasis of tumors." (PMID 36686732, 2022). "In addition, MMP-9 overexpression has also been correlated with poor prognosis in colon, gastric, lung, and pancreatic cancers." (PMID 34315513, 2021).
pancreatic cancer (continued). "It is noteworthy that the soluble protease MMP9, while not expressed in the majority of the pancreatic cancer cells and stromal cells tested here, has been implicated in PDAC progression as well." (PMID 33740019, 2021). "In addition, paeoniflorin enhanced cell apoptosis in pancreatic cancer cells via the inhibition of MMP-9 and ERK signaling pathways." (PMID 33531900, 2021). "Histological analysis verified that selenite and selenite + GMZ treatments decreased the expression of cell proliferation markers (i.e., Ki67) and that both treatments were able to inhibit MMP9, a protein closely related to the invasiveness of pancreatic cancer." (PMID 34201986, 2021). "Previous studies revealed that the tumor vasculogenesis-associated gene MMP-9 is clinically important in pancreatic cancer growth and metastasis, although MMP-9 is not among the identified genes in our microarray analysis." (PMID 29687228, 2020). "Moreover, tumor cell MMP9 levels, as well as preoperative serum MMP9 concentrations, have been found to significantly correlate with the survival of pancreatic cancer patients, identifying MMP9 as a prognostic marker for PDAC survival." (PMID 32809114, 2020). "To better understand the molecules involved in PRMT5 signalling‐induced pancreatic cancer cells invasion, we identified whether PRMT5 affected MMP2 and MMP9 expression in pancreatic cancer cells." (PMID 31851779, 2020). "Interestingly, MMP9 levels have already been shown to correlate with lymph node involvement and the occurrence of distant metastases in pancreatic cancer patients." (PMID 32809114, 2020). "Moreover, indirubin-3′-monoxime inhibits the migration and invasion of pancreatic cancer cells through the downregulation of MMP-9." (PMID 33396266, 2020). "MMP-9 is an important gene involved in pancreatic cancer growth and metastasis." (PMID 29687228, 2020). "Next, several reports have indicated that COX-2-derived PGE2 may up-regulate MMP-9 expression in pancreatic cancer or macrophages." (PMID 33228717, 2020). "PA increased the invasiveness of AsPC-1 pancreatic cancer cells via the TLR-4/ROS/NF-κB/matrix metalloproteinase-9 (MMP-9) signalling pathway and promoted metastasis in several human oral carcinoma cell lines expressing high levels of cluster of differentiation 36 (CD36)." (PMID 32526973, 2020). "Additionally, to better understand and compare the therapeutic effect of targeting MMP-2 and MMP-9 with SB-3CT, a standard chemotherapy for pancreatic cancer, i.e., gemcitabine, was used." (PMID 33251135, 2020). "Indeed, GW501516 decreased MMP-9 (Matrix Metalloproteinase-9) expression in pancreatic cancer cells and, consequently, their invasion capacity." (PMID 32519230, 2020). "However, the mechanism of abnormally upregulated MMP-2 and MMP-9 expression in pancreatic cancer from diabetic STZ and db/db mice was unclear." (PMID 33251135, 2020). "REG4, another lectin, correlated with increased expression of MMP2 and MMP9 in pancreatic cancer." (PMID 30925924, 2019). "What is more, Rg3 could downregulate the MMP9/MMP2 expression to inhibit vasculogenic mimicry in pancreatic cancer." (PMID 30915362, 2019). "This research showed that MMP-9 is a potential biomarker for pancreatic cancer." (PMID 30262739, 2018). "Moreover, the roles of MMP-2 and MMP-9 in metastasis in pancreatic cancer are also demonstrated by a positive correlation between the expression of these two MMPs and the microvessel density, suggesting their involvement in the angiogenic processes." (PMID 30301152, 2018). "We also showed that FUT175 decreases MMP-9 activity in pancreatic cancer through NF-κB modulation." (PMID 30336548, 2018). "Our data show that VEDT reversed the EMT and depleted MMP9 expression in the pancreatic tumors." (PMID 28404939, 2017).
pancreatic cancer (continued). "Additionally, down-regulation of the PI3K/Akt pathway was demonstrated to be involved in α-mangostin-reduced viability, EMT, MMP-2/MMP-9 expression, and invasion in BxPc-3 and Panc-1 pancreatic cancer cells." (PMID 28537893, 2017). "Similarly, other reports have found a dramatic increase in the activity of MMP9 in gemcitabine-resistant pancreatic cancer cells, which fits well within our molecular signaling platform of Neu1-MMP9 cross-talk in regulating growth factor receptors." (PMID 27029067, 2016). "In contrast, the MMP-9 in the prognosis of pancreatic cancer patients is still controversial." (PMID 26652622, 2015). "To investigate whether MMP-9 and TN-C are involved in the metastasis of pancreatic cancer, we further analyzed the relationship between the expression levels of MMP-9 and TN-C and the clinical characteristics of the pancreatic cancer patients." (PMID 26652622, 2015). "The data show that highly expressed miR-221/222 could inhibit TIMP-2 and further upregulate the expression of MMP-2 and MMP-9, which would promote the invasion of pancreatic cancer cells." (PMID 25883224, 2015). "Moreover, the pancreatic cancer samples that experienced recurrence of liver metastases had a stronger expression of MMP-9 and TN-C." (PMID 26652622, 2015). "The co-expression of MMP-9 and TN-C was significantly related to the pancreatic cancer metastases." (PMID 26652622, 2015). "The expression of MMP-9 and TN-C were increased in pancreatic cancer." (PMID 26652622, 2015). "Furthermore, PSCs derived Galectin-1 promotes the proliferative activity, MMP2 and MMP9 expression and invasion of pancreatic cancer cells in vitro, and tumor establishment and growth in vivo." (PMID 24595374, 2014). "Plasma CXCL7 may be degraded by exoproteases such as matrix metalloproteinase-9 (MMP9) that are secreted into the plasma by pancreatic cancer cells." (PMID 24708694, 2014). "Among them, MMP-2 and MMP-9 are highly expressed in pancreatic cancer." (PMID 24505326, 2014). "Moreover, some researches were reported that high expression of MMP-2 and MMP-9 was found in pancreatic cancer." (PMID 25496480, 2014). "It is noteworthy that others have found a dramatic increase in the activity of MMP-9 in gemcitabine-resistant pancreatic cancer cells, which fits well within our molecular signaling platform of Neu1-MMP-9 cross-talk in regulating ligand-induced receptor tyrosine kinases." (PMID 26932374, 2014). "MMPs are believed to be important facilitators of cancer cell invasion in past studies by resolving basement membrane proteins, Because of rich MMP-2 production found in the stromal cells of pancreatic cancer and the expression of MMP-9 increasing in adjacent pancreatic cancer cells." (PMID 25496480, 2014). "Miapaca-2 cells are considered a highly metastatic cell line, and our results support the idea that regulating MMP-9 expression may effectively control human pancreatic cancer cell invasion and metastasis." (PMID 23737761, 2013). "It is well known that the matrix metalloproteinases are key regulators of cell proliferation and migration in human pancreatic cancer cells and that MMP-9 protein is increased in the pancreatic juice from patients diagnosed with pancreatic ductal adenocarcinomas." (PMID 23737761, 2013). "In addition, NDRG1 inhibits the expression of VEGF and MMP-9, and suppresses the growth and angiogenesis of pancreatic cancer cells." (PMID 24269992, 2013). "The present study tested the hypothesis that PPARβ/δ is expressed in human pancreatic cancer cells and that its activation could regulate MMP-9, decreasing cancer cells ability to transverse the basement membrane." (PMID 23737761, 2013). "The relationship between MMP-9 and metastasis in pancreatic cancer is well documented." (PMID 23737761, 2013). "Furthermore, pancreatic cancer cells display extremely high basal MMP-9 expression, which is further inducible by phorbol 12-myristate 13-acetate (PMA)." (PMID 23737761, 2013).
pancreatic cancer (continued). "Our findings demonstrated that COX-2 upregulates MMP-9 expression in pancreatic cancer, and PGE2 may be involved in it." (PMID 21760774, 2011). "Of the identified differently expressed proteins, three up-regulated proteins in pancreatic cancer juice, matrix metalloproteinase-9 (MMP-9), oncogene DJ1 (DJ-1) and alpha-1B-glycoprotein precursor (A1BG), were selected for validation by Western blot and immunohistochemistry." (PMID 18706098, 2008). "Over-expression of MMP-9 and DJ-1 in pancreatic cancer tissues have been shown in previous studies." (PMID 18706098, 2008). "Therefore, MMP-9 produced by neutrophils may be a therapeutic target in pancreatic cancer treatment and provide a feasible alternative treatment for pancreatic cancer patients." (PMID 36324574, 2022). "Interestingly, the same group showed that forced expression of MMP-9 rescues the loss of angiogenesis and abrogates metastasis of pancreatic tumors triggered by the absence of host SPARC." (PMID 34298680, 2021). "To connect our discovery to clinical application, using the pancreatic carcinoma patient tissue specimen, we performed immunehistochemical staining on serial sections to access the location and expression level of Caspase-3, a dying cancer-cell marker, MMP-9, a tumor-metastasis marker, and HMGB1." (PMID 29615080, 2018). "Therefore, we evaluated the effect of VEDT on MMP9 in pancreatic cancer cells and tumor." (PMID 28404939, 2017). "Therefore, the co-expression of MMP-9 and TN-C may promote tumor metastasis and thus affect the progression of pancreatic cancer." (PMID 26652622, 2015). "However, whether the expression of TN-C and MMP-9 is involved in the clinical prognosis of pancreatic cancer patients is unclear." (PMID 26652622, 2015). "Previous observations show that upregulation of E-cadherin and a concomitant reduction in MMP-2/MMP-9 levels might negatively regulate cell proliferation, invasiveness, and adhesion of K1 papillary thyroid cancer cells and pancreatic cancer cell lines MIAPaCa-2 and BxPC-3." (PMID 24581171, 2014). "In vitro and in vivo experiments indicated that TGF-β1 upregulated Galectin-1 expression in PSCs, which could further promotes the proliferative activity, MMP2 and MMP9 expression, and invasion of pancreatic cancer cells, as well as the tumor establishment and growth." (PMID 24595374, 2014). "Indeed, fibroblast gelatinase B/MMP-9 enhances endothelial cell survival and function, gelatinase B/MMP-9 from circulating macrophages promotes angiogenesis in a model of pancreatic cancer and increased tumour cell gelatinase B/MMP-9 promotes angiogenesis in a model of neuroblastoma." (PMID 24473089, 2014). "In conclusion, our results have provided evidence that pancreatic cancer cells induce NK cell dysfunction, however NK function could be partially restored by blocking MMP-9 and/or IDO, suggesting that MMP-9 and IDO facilitate pancreatic cancer cells to evade immunosurveillance." (PMID 25274283, 2014). "However, Notch1 has also been shown to regulate the expression and activation of MMP9 through NF-κB in pancreatic cancer cells, suggesting that the regulation of MMP9 expression and activity in endothelial cells by Notch may be mediated by NF-κB signaling." (PMID 21349159, 2011). "In addition, high expression of SLUG and MMP9 is found in pancreatic cancer tissues." (PMID 22074556, 2011). "In pancreatic cancer, TNC triggers the JNK/c-Jun signaling pathway, enhancing c-Jun binding to the MMP9 promoter, thus increasing MMP9 expression levels and activity." (PMID 40046232, 2025). "In pancreatic cancer cell lines, BA treatment has been shown to inhibit the expression of NF-κB, and thus suppress COX-2 and MMP-9 genes." (PMID 40142291, 2025). "Immunohistochemistry showed that the HIF-1α/MMP2 and HIF-1α/MMP9 signaling pathways in the tumor model were blocked, proving the role of the HIF-1α/MMPs signaling pathway in the occurrence and development of pancreatic cancer." (PMID 40563539, 2025).